PDGFB (platelet derived growth factor subunit B)
Diseases named in the same sentence as PDGFB in open-access papers (continued):
Sharing a sentence is not in itself a finding about the gene and the disease.
prostate carcinoma (10 papers, 2010 to 2023). A carcinoma that arises from epithelial cells of the prostate gland. "Abnormal levels of inflammation-related serum proteins, such as C-X3-C motif chemokine ligand 1, platelet-derived growth factor subunit B homodimer, interleukin 10, C-C motif chemokine ligand (CCL) 21, and CCL 11, were also found to be related to the risk of prostate cancer." (PMID 32722165, 2020). "A prostate cancer related module was investigated (due to its significant enrichment on KEGG prostate cancer pathway), which has DEGs as PDGFRB, PDGFB, SNX2, EGFR and DECGs as (PDGFRA, PDGFRB), (SNX4, PDGFRB), (PDGFB, PDGFRA), (SNX2, PDGFRA), (PDGFRB, PIK3R2), (EGFR, PIK3R2), (EGFR, AREG)." (PMID 26070628, 2015). "Using a multicolor fluorescence in situ hybridization approach, the copy number alterations of six genes known to be involved in aggressive prostate cancer (PTEN, MYC, MEN1, PDGFB, CTTNBP2, and TBL1XR1) was explored in a group of recurrent and in a group of nonrecurrent prostate cancer patients." (PMID 31366128, 2019).
lung fibrosis (8 papers, 2014 to 2025). "Further exploration of the therapeutic effects of specific targeting of PDGFB or its receptor PDGFRB in lung fibrosis will be of interest." (PMID 38600524, 2024). "TGF-β and PDGFB are common growth factors involved in the development of multiple pulmonary diseases such as pulmonary fibrosis, pulmonary hypertension, and COPD." (PMID 37624152, 2023). "For example, lung fibrosis-associated genes (CSF3, IL8, CSF2, IL6, TNF, MMP9, IL1B and PDGFB) were significantly upregulated in SARS-CoV-2-infected NHBE cells." (PMID 32698440, 2020).
Obesity (8 papers, 2019 to 2024). Accumulation of substantial excess body fat. "The biological processes “Platelet degranulation,” “Positive regulation of glucose import” and “Cellular response to insulin stimulus,” already found modulated in obesity (PDGFB, SERPING1 ADIPOQ, PIK3R1, IGF1) were further enriched in ObCRC with respect to Ob individuals." (PMID 30838002, 2019).
oligodendroglioma (8 papers, 2011 to 2025). A well-differentiated (WHO grade II), diffusely infiltrating neuroglial tumor, typically located in the cerebral hemispheres. "The PDGFb model mimics transforming oligodendrogliomas in AYA patients, while the BRAF V600E model reflects transforming xanthoastrocytoma in pediatric patients." (PMID 40527978, 2025).
pancreatic cancer (8 papers, 2011 to 2024). "The recipient pancreatic cancer cells produce platelet-derived growth factor β (PDGFB), and recruit PSCs via PDGF receptor." (PMID 38954230, 2024). "The mechanism through which Lin28B in exosomes activates the Lin28B/let-7/HMGA2/PDGFB signaling pathway in recipient pancreatic cancer cells." (PMID 38954230, 2024). "The concentration of PDGFB is increased with decreasing distance from pancreatic cancer cells, which consequently leads to more intensive migration of PSCs." (PMID 31413760, 2019). "We verified that the pancreatic cancer cell-derived exosomes (Exo-Pan and Exo-Mia) could increase the expression level of PDGFB and promote pancreatic cancer recruitment of PSCs." (PMID 31413760, 2019). "In conclusion, pancreatic cancer cell-derived exosomes could transfer the exosomal protein Lin28B to pancreatic cancer cells, thus facilitating their recruitment of PSCs via the Lin28B/let-7/HMGA2/PDGFB pathway." (PMID 31413760, 2019). "This suggests that pancreatic cancer-derived exosomes contain few or no downstream molecules of PDGFRs; therefore, even though the exosomes were internalized by PSCs, the PDGFB/PDGFR signaling pathway could not be activated." (PMID 31413760, 2019).
renal fibrosis (8 papers, 2014 to 2025). A final common manifestation of a wide variety of chronic kidney diseases characterized by glomerulosclerosis and tubulointerstitial fibrosis. "This indicates that CCR2+PIRB‐ macrophages promote renal fibrosis by enhancing fibroblast proliferation through PDGFB secretion." (PMID 40995682, 2025). "Activated cells produce TGF‐β, IL‐6, and IL‐23, driving Th17 activation and promote the formation of myofibroblasts, while CCR2+PIRB‐ macrophages secrete PDGFB promoting fibroblast proliferation, leading to the exacerbation of renal fibrosis." (PMID 40995682, 2025). "In this study, we found that changes in a rat model of hypertensive kidney disease, including the expression of iPT cells, SPP1, IL34, and PDGFB, strongly correlated with renal fibrosis in human kidney samples obtained from patients with hypertensive and diabetic kidney disease." (PMID 37906287, 2024). "PDGFB/PDGFRB signaling has been associated with fibrosis; for example, constitutive activation of PDGFRB in mesenchymal cells has been shown to result in spontaneous renal fibrosis, while inhibition of PDGFB or PDGFRB has reduced fibrosis in experimental CKD models." (PMID 40952790, 2025). "Most strikingly, in our study, we found that FATP2 can regulate the progression of renal fibrosis by mediating the secretion of several profibrotic cytokines (TGF-β, CTGF, PDGFB, FGF2), but the specific mechanism remained unclear." (PMID 33219209, 2020). "Additionally, we found that endothelial dysfunction promoted renal fibrosis not through endothelial-to-mesenchymal transition, as previously expected, but by inducing the expression of profibrotic PDGFB in tubular epithelial cells, a process that is inhibited by TIE2 activation." (PMID 40952790, 2025).
diabetes (7 papers, 2020 to 2026). "TECs in diabetes undergo endothelial-to-mesenchymal transition and exhibit reduced PDGFB expression, while Leydig and testicular peritubular cells downregulate PDGFRB, collectively weakening intercellular connectivity." (PMID 41643060, 2026).
fibrosarcoma (7 papers, 2011 to 2024). A malignant mesenchymal fibroblastic neoplasm affecting the soft tissue and bone. "Notable, among these fusions are in-frame fusions of the collagen genes (exon 6 COL1A2, exon 20 COL1A2 and exon 35 COL3A1) with exon 2 of PDGFB in tumors of the H2 fibrosarcoma cluster which was associated with extracellular matrix and G-protein coupled receptor signaling pathways." (PMID 37369741, 2023).
malignant glioma (6 papers, 2004 to 2024). A grade III or grade IV glioma arising from the central nervous system. "In malignant glioma, CECR1 regulates PDGFB production in M2 TAMs, and TAM-derived PDGFB could promote PDGFRβ+ pericyte migration and secretion of VEGF-A and the proangiogenic ECM component periostin, thereby contributing to new vessel formation." (PMID 38303024, 2024).
ovarian carcinoma (6 papers, 2017 to 2023). A malignant neoplasm originating from the surface ovarian epithelium. "In parallel with the mRNA expression, the staining of PDGFB in ovarian cancer tissues was higher compared to normal tissues, and PDGFB was predominantly expressed by tumor cells." (PMID 36199822, 2022). "Even though the difference in PDGFB expression between the two groups was not statistically significant, we can still observe a moderate increase of PDGFB in ovarian cancer stromal components." (PMID 36199822, 2022). "The results showed a higher expression of PDGFA and PDGFB in ovarian cancer related to a poorer clinical survival (worse OS and PPS for PDGFA, worse PPS for PDGFB)." (PMID 36199822, 2022). "In ovarian cancer, PDGFB (P < 0.05), PDGFD (P < 0.05), PDGFRA (P < 0.001), and PDGFRB (P < 0.001) had a significant positive correlation with macrophage M2 infiltration, and PDGFA had a negative association with macrophage M1 infiltration (P < 0.01)." (PMID 36199822, 2022). "In ovarian cancer, KDM4B is induced under hypoxia, and deletion of KDM4B increases H3K9me3 level at target gene promoters such as the LOXL2, LCN2, and PDGFB promoters, thereby inhibiting the invasion, migration and globulization of ovarian cancer cells." (PMID 35186950, 2021). "Thus, the results of this study indicated that EGFL6 could regulate cell proliferation, migration, and angiogenesis in ovarian cancer cells by regulating the FGF-2/PDGFB signaling pathway." (PMID 32983976, 2020). "Intriguingly, the expression levels of PDGF ligands in tumor cells were inconsistent, as PDGFA and PDGFB stained strongly, whereas PDGFC and PDGFD stained weakly in ovarian cancer tumor cells." (PMID 36199822, 2022). "Except for PDGFB, the rest six genes of the PDGF family were substantially increased in the stromal components of ovarian cancer compared with epithelial components." (PMID 36199822, 2022).
Primary Familial Brain Calcification (6 papers, 2015 to 2024). "Mutations in PDGFRβ and its ligand, PDGFB, are linked to the genetic disorder idiopathic basal ganglia calcification (IBGC)." (PMID 34082828, 2021). "Genes implicated in Fahr's disease include PDGFB, PDGFRB, SLC20A2, XPR1, MYORG, and JAM2." (PMID 37780723, 2023). "Primary Familial Brain Calcification (PFBC), a neurodegenerative disease characterized by progressive pericapillary calcifications, has recently been linked to heterozygous mutations in PDGFB and PDGFRB genes." (PMID 26599395, 2015).
pulmonary hypertension (6 papers, 2021 to 2024). Increased pressure within the pulmonary circulation due to lung or heart disorder. "TWIST1 also mediates hypoxia-induced pulmonary hypertension by endothelial-to-mesenchymal transition (EndMT) as well as by changing PDGFB expression in ECs." (PMID 34660572, 2021). "In addition, among the DEGs involved in the hypoxic pathway in IPAH, the expression of CAV1, JUN, and PDGFB, which promote the progression of pulmonary hypertension, were all increased." (PMID 38586587, 2024).
fibrosis (5 papers, 2017 to 2024). the formation of excess fibrous connective tissue in an organ or tissue in a reparative or reactive process. "The impact of PDGFB and other platelet-derived cytokines in different pathologies warrants further investigation and platelet-targeting therapies may represent an interesting therapeutic strategy, for example, in fibrosis." (PMID 35454853, 2022).
hepatocellular carcinoma (5 papers, 2011 to 2022). A malignant tumor that arises from hepatocytes. "Irradiation significantly upregulated the mRNA expressions of FasL, TRAIL, TNF-α, and TGF-β1 in hepatoma cells, and downregulated the mRNA expressions of IGF-1 and PDGFB, but no obvious effects on the expressions of VEGFA, PDGFA, and IL-6." (PMID 27431384, 2016).
lymph node metastasis (5 papers, 2010 to 2022). "Moreover, the expression variability of PDGFB and its cognate receptor were found to be closely associated with lymph node metastasis and outcomes in patients." (PMID 35672821, 2022). "The elevated mRNA levels of PDGFA and PDGFB correlated significantly with lymph node metastasis (p = 0.002 and p = 0.011, respectively)." (PMID 32235327, 2020). "We found positive correlations of the mRNA levels of PDGFA, PDGFB, and PDGFRB with lymph node metastasis and poor overall survival (OS)." (PMID 32235327, 2020).
uterine sarcoma (5 papers, 2023 to 2025). "The collagen type-1 alpha-1 (COL1A1) and platelet-derived growth factor beta chain (PDGFB) fusion uterine sarcoma is a relatively new entity that is not yet listed in the 2020 WHO classification of female genital tumors, with only a few cases reported." (PMID 39064514, 2024).
breast tumor (4 papers, 2016 to 2024). "Both PDGFA and PDGFB were expressed in breast tumor samples in this study and their mRNA transcript levels were positively correlated." (PMID 39302921, 2024). "Furthermore, PDGF signaling has been found to play an active role in breast tumor progression and PDGFRB has previously been theorized—along with its cognate ligand PDGFB—to be a potential therapeutic target for multiple human cancers, including breast." (PMID 37200395, 2023).
diabetic retinopathy (4 papers, 2010 to 2023). "PDGFB is involved in the recruitment of pericytes to newly formed blood vessels in the course of physiological angiogenesis during retinal development, as well as in the context of pathological neovascularization that occurs in diabetic retinopathy and AMD." (PMID 36614910, 2022). "PDGFB elevated levels and its induction by PKC activation has been shown to be involved in pathogenesis of diabetic retinopathy." (PMID 20122255, 2010).
Alzheimer disease (3 papers, 2016 to 2020). A progressive, neurodegenerative disease characterized by loss of function and death of nerve cells in several areas of the brain leading to loss of cognitive function such as memory and language. "To determine if trisomy of chromosome 21 sequences other than APP is sufficient to modify Alzheimer’s disease-related phenotypes, we crossed Tc1 mice with the APP transgenic mouse strain Tg(PDGFB-APPSwInd)20Lms (J20-tgAPP)." (PMID 29945247, 2018).
asthma (3 papers, 2018 to 2024). "Although PDGFB is associated with alterations in airway remodelling in asthma, a link to PDGFD has not been made." (PMID 29551627, 2018). "PDGFB and PDGFR-beta mRNA in lung tissue appear more frequently in patients with asthma than with COPD; however, PDGF and its receptor do not correlate closely with structural changes in diseased airways." (PMID 38203236, 2023).
clear cell renal carcinoma (3 papers, 2022 to 2024). A malignant epithelial neoplasm of the kidney characterized by the presence of lipid-containing clear cells within a vascular network. "It regulates the transcription of PDGFB to activate the mTOR signaling pathway, thereby regulating lipid metabolism to promote the progression of renal clear cell carcinoma." (PMID 37391422, 2023). "However, a study on clear-cell renal carcinoma has found that high expression of PDGFB significantly inhibits tumor growth (p ≤ 0.05) and decreases cancer-specific mortality (p ≤ 0.001)." (PMID 35378770, 2022).
Cognitive impairment (3 papers, 2019 to 2023). Abnormal cognition is characterized by deficits in thinking, reasoning, or remembering. "Moreover, loss-of-function mutations in the PDGFB gene within the endothelium or in the PDGFRB gene within pericytes can cause primary familial brain calcification, which is characterized by pericyte loss and neurological symptoms including motor and cognitive impairments." (PMID 37958635, 2023).
endothelial dysfunction (3 papers, 2023 to 2025). In vascular diseases, endothelial dysfunction is a systemic pathological state of the endothelium (the inner lining of blood vessels) and can be broadly defined as an imbalance between vasodilating and vasoconstricting substances produced by (or acting on) the endothelium. "In response to SARS-CoV-2 infection, PDGFB may be upregulated, leading to increased angiogenesis and endothelial dysfunction." (PMID 37239234, 2023). "In this study, we investigated how endothelial dysfunction and inactivation of TIE2 signaling in CKD affect tubular injury and PDGFB-driven tubulointerstitial fibrosis." (PMID 40952790, 2025).
heart failure (3 papers, 2019 to 2024). Inability of the heart to pump blood at an adequate rate to meet tissue metabolic requirements. "PDGFB has been shown to inhibit heart failure through a mutant mouse PDGFB gene knockout, resulting in an increased congestive heart failure." (PMID 33003647, 2020).
Hypercholesterolemia (3 papers, 2021 to 2024). An increased concentration of cholesterol in the blood. "For example, serum PDGFB level was elevated in patients with hypertension and hypercholesterolemia." (PMID 39720896, 2024).
meningioma (3 papers, 2015 to 2021). A generally slow growing tumor attached to the dura mater. "Specifically, the positive rate and the immunostaining intensity of PDGFB and PDGFB receptor were higher in atypical meningiomas than in benign ones." (PMID 34885009, 2021).
osteoporosis (3 papers, 2022 to 2025). A condition of reduced bone mass, with decreased cortical thickness and a decrease in the number and size of the trabeculae of cancellous bone (but normal chemical composition), resulting in increased fracture incidence. "Furthermore, several studies highlighted PDGFB as possible therapeutic target for osteoporosis." (PMID 35580864, 2022).
Stroke (3 papers, 2020 to 2025). Sudden impairment of blood flow to a part of the brain due to occlusion or rupture of an artery to the brain. "In support of this idea, previous studies showed that brain endothelial-cell-derived trophic factors, such as PDGFB and basic fibroblast growth factor, promote the induction of PDGFRβ+ pericytes within ischemic areas after stroke." (PMID 32887241, 2020).
acute myocardial infarction (2 papers, 2024). Necrosis of the myocardium, as a result of interruption of the blood supply to the area. "They found that the expression of PDGFA, PDGFD and PDGFRB in the infarcted myocardium were increased after myocardial infarction, whereas PDGFB and PDGFC mRNAs were reduced and protein levels at infarcted myocardium were all significantly reduced in the early stage of myocardial infarction." (PMID 39569832, 2024). "In addition, results of an animal study showed that mRNA expressions of PDGFA, PDGFB, PDGFC, PDGFD and PDGFRs exhibited different changes in the infarcted rat heart in the early and late stages after myocardial infarction." (PMID 39569832, 2024).
Ataxia (2 papers, 2015 to 2023). Ataxia refers to impaired coordination of voluntary muscle movement. "The patient with a homozygous JAM2 mutation developed ataxia at age 31, while the patient with a heterozygous PDGFB mutation developed dizziness and fever at 18 years old." (PMID 37237429, 2023).
Breast Invasive Carcinoma (2 papers, 2019 to 2021). "In invasive breast cancer cells, AF1q further induced pYSTAT3 levels through the Src kinase-driven PDGFB/PDGFRB cascade." (PMID 31671695, 2019).
calcification (2 papers, 2022 to 2024). Process by which organic tissue becomes hardened by the physiologic deposit of calcium salts. "The following characteristics were found in patients with primary brain calcification with PDGFB variants." (PMID 36206226, 2022).
chordoma (2 papers, 2025). Chordomas are rare malignant tumors arising from embryonic remnants of the notochord in axial skeleton. "The presence of PDGFB and its ligands has been described previously in chordomas and has been correlated with a poor prognosis." (PMID 41228286, 2025). "In the phase II trial with imatinib in PDGFRB/PDGFB-expressing chordomas, the clinical benefit rate (CBR) (CR + PR + SD per RECIST) was 64% after 6 months, with 1 PR and 30 SDs and a median PFS of 9 months." (PMID 40627883, 2025).
depression (2 papers, 2024 to 2025). "Headache was reported in 26% of subjects (especially in PDGFB mutation carriers), anxiety or depression in 62%, psychosis or hallucinations in 10–12%, sleep disturbances in 34%; 14% of patients reported hyposmia, 32% constipation, and 34% urinary disturbances." (PMID 38999439, 2024).
diabetic kidney disease (2 papers, 2023 to 2024). Progressive kidney disorder caused by vascular damage to the glomerular capillaries, in patients with diabetes mellitus. "The expression of PDGFB in the kidney of diabetic nephropathy patients is significantly increased." (PMID 37538798, 2023).
E. coli infection (2 papers, 2019 to 2024). "Meningitic E. coli infection can induce VEGFA, PDGFB, and ANGPTL4 expression, aggravating infection-dependent BBB dysfunction." (PMID 38233877, 2024). "Therefore, we hypothesized that VEGFA, PDGFB, and ANGPTL4 may be the potential target genes of Egr-1 in meningitic E. coli infection of hBMEC." (PMID 38233877, 2024).